BRCA1 (BRCA1 DNA repair associated)
Diseases named in the same sentence as BRCA1 in open-access papers (continued):
Sharing a sentence is not in itself a finding about the gene and the disease.
ovarian carcinoma (continued). "It has been shown that BRCA1/2 germline mutations contribute to 10–15% of cases, and analysis of data from The Cancer Genome Atlas Project (TCGA) has also shown that that BRCA1/2 germline mutation, somatic mutations and promoter methylation effect ovarian cancer survival." (PMID 23555554, 2013). "BRCA1-associated breast and ovarian cancer risks can be modified by common genetic variants." (PMID 23544013, 2013). "Thus, it is important for future studies to analyze DNA methylation patterns of the PARP1 promoter in the DNA methylation-associated inactivation of the BRCA1 gene in ovarian cancer." (PMID 23442605, 2013). "Due to the close interaction to BRCA1, Abraxas might be a cancer susceptibility gene and might play a role in hereditary breast and ovarian carcinoma." (PMID 23586058, 2013). "Germ line mutations in breast cancer gene 1 (BRCA1) predispose women to breast and ovarian cancers." (PMID 23388117, 2013). "In contrast, AGTR1 expression was increased in non-BRCA1-mutated ovarian cancer." (PMID 24321324, 2013). "Similarly, in a recent Australian study, 8.8% (88/1001) of ovarian cancer patients tested had a BRCA1 mutation." (PMID 23536787, 2013). "Apart from breast and ovarian cancer, BRCA1 and BRCA2 carriers might be at higher risk for additional malignancies such as prostate, colorectal, familial melanoma and pancreatic cancers." (PMID 23935836, 2013). "BRCA1 mutation carriers have increased and variable risks of breast and ovarian cancer." (PMID 23544013, 2013). "In addition, the overexpression of BRCA1 can effectively reduce the expression of EGFR in BRCA1-mutated ovarian cancer cells." (PMID 24321281, 2013). "We have also identified 2 novel loci associated with ovarian cancer for BRCA1 mutation carriers." (PMID 23544013, 2013). "Variants of BRCA1 are markers for breast and ovarian cancers, but it is unclear whether mutations in this gene increase the risk of CRC." (PMID 23496813, 2013). "In 2003, Cass and colleagues made the surprising observation that a group of ovarian carcinoma patients with BRCA1 and BRCA2 mutations had a significantly higher (72%) response rate to primary platinum-based chemotherapy than patients with sporadic disease (36%)." (PMID 23344037, 2013). "BRCA1- or BRCA2-mutated ovarian cancer patients are defective of the mechanisms of DNA repairing." (PMID 23577259, 2013). "However, clinicopathologic studies have shown most ovarian cancers with germline BRCA1 and BRCA2 mutations to be morphologically and clinically similar to sporadic ovarian cancer." (PMID 23289505, 2013). "Germline mutations of BRCA1/2 are associated with hereditary breast and ovarian cancer." (PMID 22809218, 2012). "The lifetime risks of ovarian cancer are 54% for BRCA1 and 23% for BRCA2 mutation carriers." (PMID 22330607, 2012). "The uptake of surgery was related to risk of developing ovarian cancer as demonstrated by a significantly higher uptake in BRCA1 mutation carriers, who have a lifetime ovarian cancer risk of 39–65%, compared with BRCA2 mutation carriers, whose lifetime risks are 10–37%." (PMID 22187038, 2012). "Multiple studies have found mutations in the BRCT domain of BRCA1 in breast and/or ovarian cancers." (PMID 22737296, 2012). "Our results are in line with the notion that MMR genes may predispose to a biologically different type of ovarian cancer than BRCA1/2 or in the general population, characterized by early stage disease at presentation and favorable prognosis." (PMID 22234272, 2012). "Inherited mutations in the BRCA1 gene predispose to a higher risk of breast/ovarian cancer." (PMID 24278741, 2012). "10%–15% of women with ovarian cancer have genetic predispositions of BRCA1 and BRCA 2 mutations." (PMID 22235203, 2012). "In addition, we also used a unique IOSE cell line, IOSE 592F, which was developed from an ovarian cancer patient harboring mutation in BRCA1 gene [in exon 11, position 3819del5 (GTAAA)]." (PMID 22685544, 2012).
ovarian carcinoma (continued). "Between 1997 and 2012, more than 13.000 families fulfilling the criteria for hereditary breast and ovarian cancer were tested for mutations affecting the major susceptibility genes BRCA1 and BRCA2 by the German Consortium of Hereditary Breast and Ovarian Cancer (GC-HBOC)." (PMID 23239986, 2012). "Wild-type BRCA1/2 genes are critical for DNA repair by the homologous recombination (HR) pathway—hence their deletion causes genomic instability and predisposes affected females to familial breast and ovarian cancers." (PMID 22481932, 2012). "Germline mutations in BRCA1 predispose to breast and ovarian cancer." (PMID 22347400, 2012). "Additionally, BRCA1-associated ovarian cancers often show high grade serous histology, whereas HNPCC-associated ovarian cancers often display endometrioid histology." (PMID 23164213, 2012). "To test if PCGT and MESC methylation changes are also present in cells which are not immediately involved in carcinogenesis we studied white blood cell DNA from women who carry BRCA1 mutations and who are therefore at an 80% lifetime risk of developing breast and/or ovarian cancer." (PMID 22346766, 2012). "In BRCA1 mutation carriers we found an elevated OR for ovarian cancer related to the SNP309TG and SNP309GG genotypes (SNP309TG; OR 1.53; CI 1.07-2.19; p = 0.020; SNP309GG; OR 1.92; CI 1.19-3.10; p = 0.009; SNP309TG + GG combined: OR 1.61; CI 1.15-2.27; p = 0.005)." (PMID 23039163, 2012). "This is exemplified by a study concerning inherited missense mutations of the tumor suppressor gene, BRCA-1, which may predispose to breast or ovarian cancer." (PMID 23049726, 2012). "BRCA1 is a tumor suppressor gene whose mutations lead to breast and/or ovarian cancer." (PMID 22646717, 2012). "It is possible that the improved adjuvant options such as use of aromatase inhibitors in BRCA2 carriers, who have predominantly suffered from ER-positive breast cancers, could have equalised the effect of higher risk of ovarian cancer in BRCA1 carriers." (PMID 22187038, 2012). "BRCA1/2, thus, accounts for 10 to 15 percent of all ovarian cancer risk, with other cancers also demonstrating increased prevalence in association with BRCA1 (uterine cervix and corpus, pancreas and colon) and BRCA2 (pancreas, stomach, gallbladder, bile ducts and malignant melanoma)." (PMID 22984553, 2012). "Interestingly, only 5–10% of women with ovarian cancer have inherited genetic mutations in tumor suppressor genes such as BRCA1 and BRCA2 that predisposes them to breast and ovarian cancer." (PMID 22685544, 2012). "Thus, two triple negative breast cancers and the presence of an ovarian cancer strongly suggested a BRCA1-associated disease in this family." (PMID 23164213, 2012). "The BRCA1 gene encodes a transcription factor involved in recombination and DNA repair and reduced levels of BRCA1 as well as mutations in its sequence significantly increase susceptibility to breast and ovarian cancer." (PMID 22852056, 2012). "The lower incidence of the SNP285C/309G haplotype found in BRCA1 mutation carriers with ovarian cancer may indicate a risk reducing effect of the SNP285C allele." (PMID 23039163, 2012). "BRCA1 mutations also confer a medium to high risk of ovarian cancer." (PMID 22032724, 2011). "The second ovarian cancer case was found in a 40 year old BRCA1 gene mutation carrier." (PMID 22112691, 2011). "The mutant phenotype of BRCA1 predisposes to breast and ovarian cancer." (PMID 21211025, 2011). "The aim of these consortia’s is to combine data from many studies, to provide a reliable assessment of the breast and ovarian cancer risks associated with different genetic and environmental factors, and to identify potential modifiers of cancer risk in carriers of BRCA1 and BRCA2 mutation." (PMID 21639959, 2011). "Indeed, when all BRCA1 mutations are taken together, the prevalence of breast and ovarian cancer linked to the BRCA1 locus is one of the highest among late-onset diseases." (PMID 21483040, 2011).
ovarian carcinoma (continued). "The predictive accuracy of this gene signature was validated initially in 10 tumour biopsies from 6 patients with germline BRCA1/2 mutations and in 70 patients with sporadic ovarian cancer and significant correlation was noted with platinum sensitivity and clinical parameters including survival." (PMID 21989215, 2011). "The pooled analysis of 50 ovarian cancer patients with BRCA1/2-mutation treated on phase I and II studies (11 on phase I, and 39 on phase phase II receiving olaparib 200 mg twice daily) showed RR of 40% and DCR of 46%, predominately in platinum-sensitive group." (PMID 21504625, 2011). "In women with a known BRCA1 or BRCA2 gene mutation the cumulative life-time risk of developing ovarian cancer can be as high as 60% and 27%, respectively, although it may be between 11-39% if the family history is less strong." (PMID 22112691, 2011). "The most common mutations in the BRCA1 gene in the families with an increased risk of breast and/or ovarian cancer in Slovenia are c.181T > G, c.1687C > T, c.5266dupC, c.844_850dupTCATTAC and c.181T > A. The most frequent mutations in BRCA2 are c.7806-2A > G, c.5291C > G and c.3975_3978dupTGCT." (PMID 21232165, 2011). "Since the establishment of the link between breast and ovarian cancers and BRCA1/2 genes mutations, in addition to the increasing availability of genetic testing, research groups were faced with many questions concerning the efficacy and usefulness of risk-reducing surgery." (PMID 20961453, 2010). "However, the future of personalised medicine in patients affected by ovarian cancer is dependent on the development of a robust qualified assay for detecting homologous recombination-defective tumours and the mechanism of BRCA1/2 loss." (PMID 24281034, 2010). "Mutations of BRCA1/2 are associated with increased susceptibility for breast and ovarian cancer." (PMID 23554638, 2010). "The breast and ovarian cancer susceptibility gene BRCA1 maps to 17q21 and could be one possible gene target, but the actual pathogenetic involvement of this and other genes located in 17q needs to be further investigated." (PMID 20184781, 2010). "In order to fulfil the assumption of the economic efficacy of the screening test, only founder mutations in the BRCA1 gene were searched for and testing was offered only to the persons who reported at least one case of breast and/or ovarian cancer in the family." (PMID 21034437, 2010). "Moreover, BRCA1 germline mutation carriers are not only at risk of ovarian cancer, but also fallopian tube carcinoma and peritoneal papillary serous carcinoma." (PMID 20961453, 2010). "BRCA1 mutations have a higher incidence in ovarian cancer than BRCA2 mutations do." (PMID 23554638, 2010). "Germline mutations in BRCA1 cause extremely high predisposition to breast and ovarian cancers." (PMID 21103343, 2010). "In addition, women with inherited mutations of BRCA1 gene are also predisposed for ovarian cancer with a lifetime risk about 37-62% compared to less than 2% for women that do not carry BRCA1 or BRCA2 mutations." (PMID 21054854, 2010). "Low levels of BRCA1 mRNA were associated with longer survival in a retrospective cohort of lung cancer patients following cisplatin gemcitabine and in two retrospective cohorts of ovarian cancer patients treated with platinum-based chemotherapy." (PMID 20209131, 2010). "Similarly, BRCA1/2 mutation carriers with ovarian cancer show higher response rates and longer overall survival after platinum-based chemotherapy than nonhereditary patients." (PMID 19904273, 2009). "BRCA1-associated ovarian carcinomas in women typically exhibit serous histology." (PMID 20046879, 2009).
ovarian carcinoma (continued). "The most consistently reported difference is in the distribution of tumor histologies; BRCA1 mutation carriers tend almost exclusively to develop serous ovarian cancer, whereas a considerable fraction of sporadic ovarian cancers are of endometrioid, mucinous, or clear-cell histology." (PMID 19636370, 2009). "Very recently a phase II trial with olaparib has been reported in BRCA1/2 deficient ovarian cancer." (PMID 19825178, 2009). "It is also worth noting that our analysis adds to a growing body of evidence that “ovarian” cancers occur frequently in the Fallopian tubes—we found that occult serous “ovarian” cancers in BRCA1 mutation carriers are approximately twice as likely to be found in the Fallopian tubes as in the ovaries." (PMID 19636370, 2009). "The BRCA1 is a tumor suppressor gene associated with breast and ovarian cancer risk." (PMID 19865540, 2009). "Given that aromatase is critical in promoting tumour growth and BRCA1 and 2 mutations account for an 80% increased risk in hereditary breast and ovarian cancer development, it is important to investigate the relationship between BRCA1 and aromatase expression in patients." (PMID 19445691, 2009). "To determine the most appropriate risks for women attending clinical cancer genetics services we determined the cumulative risks of breast and ovarian cancer for 385 families with pathogenic BRCA1/2 mutations identified in North West and Central England covering a population of 10 million." (PMID 18513387, 2008). "Moreover, there are examples of E3 ligases themselves functioning as oncogenes or tumour suppressor genes, including the breast and ovarian cancer susceptibility gene BRCA1." (PMID 18349819, 2008). "A comparison of clinical outcomes between ovarian cancer patients with BRCA1 promoter hypermethylation to patients with BRCA1 mutations and wild-type BRCA1 genes demonstrated that patients with BRCA1 promoter hypermethylation had significantly shorter survival times compared to the other two groups." (PMID 18208621, 2008). "The molecular mechanism underlying the relationship between loss of PTEN and BRCA1 mutations in ovarian cancer remains unknown." (PMID 18628764, 2008). "Notably, over 80% of ovarian cancers exhibit loss of BRCA1 and/or BRCA2 function, leading to compromised DNA repair." (PMID 18923710, 2008). "In addition, we found that ovarian carcinomas with loss of BRCA1 through genetic events and those with BRCA1 loss through epigenetic events both have activation of the PI3K/AKT pathway, though the mechanism of activation is different." (PMID 18208621, 2008). "In addition, human BRCA1-associated breast and ovarian cancers are multifocal and frequently arise in the contralateral breast." (PMID 18394172, 2008). "Since nothing is known about the influence of the PHB 3'UTR polymorphism on hereditary ovarian cancer risk, we performed a case-control study among Polish women carrying one of the three common BRCA1 founder mutations, comprising 127 ovarian cases and 127 matched controls." (PMID 18397521, 2008). "We have previously reported that knockdown of BRCA1 in ovarian granulosa cells results in elevated aromatase basal expression, providing a molecular explanation for why loss of BRCA1 predominantly leads to breast and ovarian cancers in women." (PMID 19568323, 2008). "Ovarian carcinomas in patients with BRCA1, in contrast are associated with a favourable prognosis." (PMID 18208621, 2008).
ovarian carcinoma (continued). "Different histological subtypes may show different genetic association, e.g, the proportion of serous tumours is higher in BRCA1 associated ovarian cancer." (PMID 17342202, 2007). "Furthermore, there are two common Ashkenazi Jewish (AJ) founder BRCA1 mutations, 185delAG and 5382insC, initially identified in linkage studies of multiple-case breast/ovarian cancer families." (PMID 17916242, 2007). "In addition, several studies have reported better survival in patients with hereditary BRCA1-associated ovarian carcinoma compared with those with sporadic carcinoma." (PMID 19690636, 2007). "A novel BRCA1 mutation, E1373X in exon 12, was found in a patient affected with ovarian cancer." (PMID 17233897, 2007). "Therefore, it is unlikely that annual screening will reduce mortality from ovarian cancer in BRCA1/2 mutation carriers." (PMID 17426707, 2007). "For instance, BRCA1/2 are the two major breast and ovarian cancer susceptibility genes." (PMID 17242703, 2007). "However, a small carboxyl-terminal BRCA1 truncation caused defective transcriptional activation, cell cycle progression, and increased sensitivity to double-strand breaks in an ovarian cancer cell line." (PMID 16417649, 2006). "The loss of BRCA1 function thus appears to be a double-edged sword: it may increase sensitivity to chemotherapy commonly used in breast and ovarian cancer and translate into favourable prognosis, but on the other side, it may trigger secondary leukaemogenesis." (PMID 17047656, 2006). "Of all ovarian cancers, 5% to 10% are hereditary, and most of these (65% to 75%) belong to the hereditary breast-ovarian cancer syndrome group that is linked to mutations in BRCA1 or BRCA2 tumour suppressor genes." (PMID 15345077, 2004). "Given the proportion of all breast/ovarian cancer families in our population attributable to recurring mutations, a cost-effective stepwise molecular screening strategy of BRCA1 and BRCA2 may be applied in the future." (PMID 15026808, 2004). "However, since the prevalence of BRCA1 mutations in the Norwegian population was low, the proportion of ovarian cancers due to BRCA1 mutations seemed to be low, about 4%." (PMID 15477862, 2004). "Individuals identified as BRCA1/2 gene mutation carriers can potentially reduce the risk associated with breast/ovarian cancer by electing to undergo risk-reducing surgery, chemoprevention, or regular surveillance to detect cancer at an early stage when it is more treatable." (PMID 15505627, 2004). "In addition, an EST (clone ID 32930) belonging to this same unigene cluster was found to be significantly higher expressed in BRCA1-associated ovarian cancers compared to sporadic tumors." (PMID 15383145, 2004). "In summary, this study showed that BRCA1 mutation carriers have a very high risk of ovarian cancer." (PMID 15477862, 2004). "Most ovarian carcinomas in women with BRCA1 mutations have been reported to be of serous histology." (PMID 15477862, 2004). "However, since the prevalence of BRCA1 mutations in the Norwegian population was low, the proportion of ovarian cancers due to BRCA1 mutations seemed to be low." (PMID 15477862, 2004). "This study showed that BRCA1 mutation carriers have a very high risk of ovarian cancer." (PMID 15477862, 2004). "Second, the later study also includes 42 BRCA2 carriers (43%), while the incidence in our series is established for BRCA1 carriers who have a higher intrinsic ovarian cancer risk, and this may also be true for PPSC." (PMID 15083174, 2004). "Women with mutations of the genes BRCA1 or BRCA2 are at increased risk of ovarian cancer." (PMID 15545966, 2004). "Controversy concerning the subcellular localisation of the BRCA1 protein has abounded, with it being reported as nuclear, nuclear in normal but cytoplasmic in breast and ovarian carcinoma cells, membrane associated on the cytoplasmic aspect of nuclear invaginations, or a secreted growth inhibitor." (PMID 12698194, 2003).